RN7SL442P (RNA, 7SL, cytoplasmic 442, pseudogene)
Gene: Miscellaneous RNA gene on chromosome 17 (16,191,832 to 16,192,151, forward strand). Ensembl gene ENSG00000239221.
Homologues: Orthologues: chimpanzee Metazoa_SRP (99% identical), macaque Metazoa_SRP (90% identical). Paralogues in human: RN7SL1 (75% identical), RN7SL3 (75% identical), RN7SL2 (74% identical), RN7SL45P (73% identical), RN7SL126P (73% identical), RN7SL612P (73% identical), RN7SL664P (73% identical), RN7SL679P (72% identical), RN7SL448P (72% identical), RN7SL118P (72% identical), RN7SL230P (72% identical), RN7SL296P (72% identical), and 698 more.